OR9K2 (olfactory receptor family 9 subfamily K member 2)
Description:
Odorant receptor.
Synonyms: OR12-2
Gene: Protein-coding gene on chromosome 12 (55,126,406 to 55,132,750, forward strand). Ensembl gene ENSG00000170605.
Subcellular location: Cell membrane
Pathways (Reactome):
Sensory Perception: Expression and translocation of olfactory receptors
Genetic constraint (gnomAD): Loss-of-function variants: 14 observed, 11.47 expected, observed/expected ratio (o/e) 1.22, 90% interval 0.8 to 1.8. The upper end of that interval is the gene's LOEUF score, 1.8, which puts it in group 6 of 6, group 1 being the genes least tolerant of losing a copy. Missense variants: 396 observed, 361.17 expected, observed/expected ratio (o/e) 1.1, 90% interval 1.01 to 1.19. Synonymous variants: 119 observed, 128.88 expected, observed/expected ratio (o/e) 0.92, 90% interval 0.8 to 1.08.
Homologues: Orthologues: chimpanzee OR9K2 (98% identical), dog OR9K2 (89% identical), mouse Or9k2 (89% identical), mouse Or9k2b (88% identical), rat Or9k2b (88% identical), dog OR9K2C (86% identical), dog OR9K2D (86% identical), guinea pig OR9K2 (85% identical), rabbit OR9K2 (83% identical). Paralogues in human: OR9H1 (50% identical), OR8I2 (49% identical), OR5B12 (48% identical), OR5AP2 (48% identical), OR5I1 (48% identical), OR5A1 (47% identical), OR5B21 (47% identical), OR5M11 (47% identical), OR9G4 (47% identical), OR5D18 (46% identical), OR5L2 (46% identical), OR8A1 (46% identical), and 84 more.